JAK2 (Janus kinase 2)
Diseases named in the same sentence as JAK2 in open-access papers (continued):
Sharing a sentence is not in itself a finding about the gene and the disease.
head and neck squamous cell carcinoma (12 papers, 2012 to 2024). A squamous cell carcinoma that arises from any of the following anatomic sites: lip and oral cavity, nasal cavity, paranasal sinuses, pharynx, larynx, and salivary glands. "In head and neck squamous cell carcinoma, miR-375 acted as a modulator to increase the cellular immune response to cancer by inhibiting PD-1/PD-L1 signaling via the Janus kinase 2/signal transducer and activator of transcription 1 pathway." (PMID 33535558, 2021). "Bru-induced head and neck squamous cell carcinoma growth was similarly attributed to the disruption of the activation of STAT3 and upstream kinases such as JAK1, JAK2, and Src." (PMID 38397437, 2024). "One study suggested that lincRNA-p21 blocked the JAK2/STAT3 signaling pathway to decrease cell proliferation, thereby inhibiting the progression of head and neck squamous cell carcinoma." (PMID 37073660, 2023). "CCR7, which binds with CCL19, stimulated the phosphorylation of Janus kinase 2 (JAK2) and signal transducer and activator of transcription 3 (STAT3) in head and neck squamous cell carcinoma cell lines (PCI-4B and PCI-37B)." (PMID 36555115, 2022). "Conversely, blocking the IL-6/JAK2/STAT3 pathway can inhibit the progression of precancerous vocal cord (oral) leukoplakia and delay the occurrence of head and neck squamous cell carcinoma (HNSCC) tumors." (PMID 37666813, 2023).
lupus (12 papers, 2016 to 2025). "A selective inhibitor for JAK1 and JAK2, approved for use in rheumatoid arthritis, recently demonstrated its potential as an agent for the treatment of lupus patients." (PMID 36015084, 2022). "We also showed that inhibition of Tyk1/Jak2 with tofacitinib in lupus-prone mice produced an increase in GILZ expression, suggesting this pathway has an inhibitory effect on GILZ transcription." (PMID 36505447, 2022). "Treatment of lupus-prone mice with JAK2 inhibitors led to prevention or improvement of established disease." (PMID 30026918, 2018). "Some other authors have demonstrated that treatment of lupus-prone mice with JAK2 inhibitors led to disease prevention or improvement." (PMID 27278657, 2016). "Collectively, the present study demonstrated that baricitinib, a selective inhibitor for JAK1 and JAK2, could mitigate autoimmune features in lupus-prone mice by suppressing eccentric B cell activation and recovering structural injuries of podocytes." (PMID 34497607, 2021). "Ruxolitinib, a relatively specific inhibitor of JAK1 and JAK2, was administered to the MLR/lpr model to investigate its effect on lupus-related skin lesions." (PMID 37457579, 2023). "An amount of 5 mg/kg ART significantly decreased the expression of p-Jak2/Jak2 and p-Stat3/Stat3 better than the 2.5 mg/kg treatment, suggesting that ART has therapeutic effects on lupus-prone MRL/lpr mice and involves Tfh cells and JAK–STAT signalling pathways." (PMID 35335880, 2022).
osteoarthritis (12 papers, 2011 to 2025). A noninflammatory degenerative joint disease occurring chiefly in older persons, characterized by degeneration of the articular cartilage, hypertrophy of bone at the margins and changes in the synovial membrane. "In vitro and in vivo studies have shown that the JAK2/STAT3 pathway plays vital roles in osteoarthritis (OA)." (PMID 35563622, 2022). "Dose-dependent responses upon JAK2 inhibitor treatment resulted in reduced bone degradation, reduced tissue destruction, and reduced osteoarthritis as evidenced by the histopathology images." (PMID 21510883, 2011). "The JAK2/STAT3 pathway plays an important role in osteoarthritis (OA) pathogenesis." (PMID 35563622, 2022). "Previous studies demonstrated that inhibiting the activation of the JAK2/STAT3 pathway could alleviate the degradation of osteoarthritis chondrocytes." (PMID 35747513, 2022). "Recently, lots study showed that JAK2/STAT3 pathway play important roles in osteoarthritis." (PMID 30361290, 2018). "Previous studies showed that JAK2/STAT3 signaling pathway play important roles in osteoarthritis." (PMID 30361290, 2018). "The JAK2/STAT3 signaling pathway is a key regulator of various cellular functions, including survival, proliferation, and differentiation, and its persistent activation has been implicated in the progression of several diseases, such as interstitial lung diseases and osteoarthritis." (PMID 40361044, 2025). "The terms “JAK2”, “STAT3”, and “Osteoarthritis”were used in a comprehensive literature search in PubMed to further investigate the relationship between the JAK2/STAT3 signaling pathway and OA." (PMID 37013568, 2023). "In this review, 32 core articles were collected from PubMed, Web of Science, Embase and other platforms with "JAK2 OR STAT3" and “osteoarthritis” as keywords in recent years.." (PMID 37013568, 2023). "The apoptosis of chondrocytes activated via the JAK2/signal transducer and activator of transcription 3 (STAT3) signaling pathway in osteoarthritis in vitro and in vivo model." (PMID 31212619, 2019).
thyroid cancer (12 papers, 2020 to 2025). "In thyroid cancer, the JAK2/STAT3 signaling pathway not only directly induces the EMT process and enhances cancer cell migration but also synergistically promotes VEGF-A secretion, thereby regulating tumor metastasis and angiogenesis." (PMID 40530008, 2025). "A study on thyroid cancer cells (TCC) indicated ORI targeting JAK2 for deactivating JAK2/STAT3 pathway to ultimately suppress angiogenesis and epithelial–mesenchymal transition of TCC." (PMID 38726411, 2024). "Our studies revealed that oridonin inhibited metastatic phenotype, angiogenesis and modulated EMT in thyroid cancer in vitro and vivo through downregulation of JAK2/STAT3 signaling pathway." (PMID 35813296, 2022). "Meanwhile, the results of western blotting revealed that oridonin inhibited the angiogenesis of thyroid cancer via JAK2 signaling." (PMID 35813296, 2022). "It has been reported recently that gene JAK2 may be a latent target of oridonin in the treatment of thyroid cancer." (PMID 37221474, 2023). "Similarly, in lung cancer, the overexpression of ANXA8 activates the EGFR/AKT/mTOR signalling pathway to promote proliferation, while in thyroid cancer, increased ANXA1 promotes thyroid cancer proliferation by mediating IL-6/JAK2/STAT3." (PMID 36936694, 2023). "In thyroid cancer, this protein has been reported as a potential diagnostic and prognostic biomarker of PTC by regulating epithelial-mesenchymal transition and activating the IL-6/JAK2/STAT3 pathway." (PMID 37833989, 2023). "Taken together, these data strongly suggested that oridonin could suppress VEGFA expression via JAK2/STAT3 pathway in thyroid cancer cells." (PMID 35813296, 2022). "In addition, AG490, a JAK2 antagonist, enhanced the anti-migratory and anti-invasive effects of oridonin on thyroid cancer cells, which were confirmed by western blotting, Transwell migration assay and Matrigel invasion assay." (PMID 35813296, 2022). "It has been found that BRAF inhibitors (vemurafenib) may lead to JAK2/STAT3 signaling activation in BRAF mutant thyroid cancer cell lines." (PMID 36430869, 2022). "In addition, the findings indicated that JAK2 may be a potential therapeutic target of oridonin against thyroid cancer." (PMID 35813296, 2022). "In addition, overexpressing JAK2 could weaken the anti-metastatic capacity of oridonin in thyroid cancer." (PMID 35813296, 2022). "Metformin shows potential therapeutic value by inhibiting the mTOR signaling pathway and targeting JAK2 in the JAK2/STAT3 signaling pathway, thereby effectively inhibiting the proliferation, migration, and EMT of thyroid cancer cell lines." (PMID 40530008, 2025). "As expected, the protein levels of phosphorylated-JAK2 and phosphorylated-STAT3 were dramatically reduced upon oridonin treatment in thyroid cancer TPC-1 and BCPAP cells." (PMID 35813296, 2022). "The current study exhibited an effective decrease of p-JAK2 and p-STAT3 protein levels upon oridonin treatment in thyroid cancer TPC-1 and BCPAP cells, as evidenced by western blotting." (PMID 35813296, 2022). "Dong quai methylin downregulates the JAK2/STAT3 signaling pathway, thereby inhibiting VEGF-A expression to limit angiogenesis and directly reversing the EMT phenotype, which in turn suppresses thyroid cancer migration." (PMID 40530008, 2025). "Furthermore, through examination of the expression of JAK1, p-JAK1, JAK2, p-JAK2, STAT3, and p-STAT3 in diverse thyroid cancer cell lines, it was discovered that ATC cells exhibit elevated levels of background expression." (PMID 38336839, 2024). "Though three genes, i.e., RET, CDKN2A, and JAK2, are not enriched in a cancer related pathway with other detected genes, they are believed to have a close relationship with thyroid carcinoma." (PMID 37221474, 2023). "Interestingly, oridonin effectively repressed p-JAK2 and p-STAT3 protein levels in thyroid cancer TPC-1 and BCPAP cell lines in a concentration-dependent manner." (PMID 35813296, 2022).
thyroid cancer (continued). "We found that overexpression of JAK2 could partially reverse the change of p-STAT3, E-cadherin and N-cadherin protein levels induced by oridonin in thyroid cancer TPC-1 and BCPAP cells." (PMID 35813296, 2022). "In contrast to the results of JAK2 overexpression, our findings revealed that AG490 could further strengthen the inhibitory effect of oridonin on thyroid cancer migration and invasion." (PMID 35813296, 2022). "In thyroid carcinoma, LINC00511 could interact with TAF1 to upregulate JAK2, which then activated STAT3 signaling pathways to maintain the resistance to radiotherapy of malignant cells." (PMID 32713253, 2020). "To further confirm whether JAK2/STAT3 pathway is involved with anti-metastatic characteristic of oridonin in human thyroid cancer cells or not, we overexpressed JAK2 by transiently transfecting JAK2 plasmid." (PMID 35813296, 2022). "Thus, we hypothesized JAK2/STAT3 signaling pathway participated in the anti-migratory and anti-invasive effects of oridonin on thyroid cancer cells." (PMID 35813296, 2022). "Conversely, REX1 significantly enhances EMT-dependent migration by activating the JAK2/STAT3 signaling pathway and may indirectly promote the formation of a pro-angiogenic microenvironment, further confirming the synergistic role of EMT and angiogenesis in thyroid cancer." (PMID 40530008, 2025).
chronic eosinophilic leukemia (11 papers, 2013 to 2025). "IL-5RA intracellular signaling provoked eosinophils proliferation and exaggerated activation through FIP1L1-PDGFRA/JAK2/Lyn/Akt network complex, which manifested as chronic eosinophilic leukemia (CEL)." (PMID 34497605, 2021). "PCM1::JAK2, identified in chronic eosinophilic leukemia, leads to persistent JAK2 signaling." (PMID 40140631, 2025). "SOCS3, but not SOCS2, was also upregulated in a chronic eosinophilic leukemia bearing PCM1-JAK2, highlighting its role as a central signalling target of JAK2 translocation neoplasia." (PMID 23372669, 2013).
depression (11 papers, 2019 to 2026). "One of the key contributors to refractory depression is the dysregulation of the JAK2/STAT3 signaling pathway." (PMID 39864626, 2025). "In contrast, upregulation of miR‐204‐5p in the vmPFC of CUMS rats significantly causes inhibition of JAK2/STAT3 signaling pathway, improvements in neuronal impairments, and an abolition of the depression and anxiety‐like behaviors." (PMID 39792918, 2025). "In summary, these results provide important, new insights into the mechanisms of the miR‐204‐5p/ JAK2/STAT3 signaling pathway that may be involved with depression and may thus serve as a potential new target for the prognosis and treatment of this condition." (PMID 39792918, 2025). "Collectively, these results provide robust evidence that the miR‐204‐5p/JAK2/STAT3 pathway may critically involve in the pathogenesis of depression, which may serve as potentially critical therapeutic target in the treatment of MDD." (PMID 39792918, 2025). "The study of whether ghrelin regulates neuroinflammation when activating the Jak2/STAT3 pathway will be an important basis for comprehensively determining whether ghrelin can be used as a target for the treatment of depression." (PMID 39057075, 2024). "However, JAK2 also has important functions in an inflammation, which is important to consider in the context of depression and treatment response." (PMID 31594917, 2019). "Our findings reveal that DSS mitigates hippocampal neuroinflammation and enhances hippocampal neurogenesis in depression model mice via modulation of the TLR4/NF-κB p65, JAK2/STAT3 and AKT-GSK3β signaling pathways." (PMID 41190144, 2025). "We further investigated the effects of WP1066, a JAK2/STAT3 inhibitor, on neuroinflammation and depression-like behaviors induced by CUS." (PMID 39864626, 2025). "JAK2/STAT3 and NF‐κB signaling system may be new targets for depression treatment, and intervening in their activation pathway, it also has positive implications for the treatment of depression." (PMID 37032645, 2023). "The JAK2/STAT3 and NF‐κB pathway have been well described in depression." (PMID 37032645, 2023). "Thus, we hypothesized that miR‐204‐5p may regulate neuroinflammation and apoptosis via the JAK2/STAT3 signaling pathway, a relationship which may then be targeted for use in alleviating depression." (PMID 39792918, 2025). "We used, WP1066 or SC99, two inhibitors of the JAK2/STAT3 pathway capable of crossing the blood‐brain barrier and thus achieving therapeutic effects within the central nervous system (CNS), to evaluate the contribution of this pathway to the display of depression." (PMID 39792918, 2025). "Furthermore, ghrelin/GHSR can activate multiple signaling pathways, including cAMP/CREB/BDNF, PI3K/Akt, Jak2/STAT3, and p38-MAPK, to produce antidepressant effects, given which it is expected to become a potential therapeutic target for the treatment of depression." (PMID 39057075, 2024). "In conclusion, taVNS ameliorates depression‐like behaviors in CUMS model rats, inhibits the hypothalamic microglia activity and increases α7nAchR expression in the hypothalamus, which in turn activates the JAK2/STAT3 signaling pathway and inhibits the NF‐κB signaling pathway." (PMID 37032645, 2023).
neutropenia (11 papers, 2010 to 2025). A decrease in the number of neutrophils found in the blood. "A retrospective audit was therefore performed in order to address the value of screening for the JAK2 V617F mutation in patients presenting with neutropenia." (PMID 29383013, 2018). "While the number of patients analysed with an isolated neutropenia remains modest, this audit suggests that testing for the JAK2 V617F mutation is not warranted in patients with neutropenia unless accompanied by additional features suggestive of a myeloid malignancy." (PMID 29383013, 2018). "Since JAK2 is downstream of erythropoietin (EPO), granulocyte-macrophage colony-stimulating factor (GM-CSF), and thrombopoietin (TPO), neutropenia has been found in clinical trials with the JAK inhibitors baricitinib and tofacitinib both of which target JAK2 to some extent." (PMID 33343569, 2020). "Since experimental evidence suggests neutropenia is generally not observed using potent Jak inhibitors in rodents or human patients at doses in which Jak2 is inhibited for less than 8 hours, CC-509 will be unlikely to induce neutropenia in human patients at exposures predicted to be efficacious." (PMID 26756335, 2016).
acute lung injury (10 papers, 2017 to 2026). A condition of lung damage that is characterized by bilateral pulmonary infiltrates (pulmonary edema) rich in neutrophils, and in the absence of clinical heart failure. "In the rat model of acute lung injury (ALI), anisodamine suppressed bleomycin-induced inflammation, oxidative stress, and apoptosis in ALI rats by inhibiting the JAK2/STAT3 pathway." (PMID 39857375, 2025). "JAK2 and STAT3 were verified as a hub pathway to modulating oxidative stress, inflammation, and cell apoptosis in a model of bleomycin-induced acute lung injury rat." (PMID 35132912, 2022).
alopecia areata (10 papers, 2016 to 2025). Loss of scalp and body hair involving microscopically inflammatory patchy areas. "Baricitinib, a selective JAK1/JAK2 inhibitor, is the first targeted therapy approved by the FDA for systemic treatment of alopecia areata (AA)." (PMID 38903518, 2024). "JAK3 was strongly expressed also in alopecia areata; JAK1 and JAK2 were to a lesser extent also elevated." (PMID 37624299, 2023). "This was confirmed by the rapid onset of anagen followed by hair growth in mouse and human skin after administering selective and reversible inhibitors of JAK1 and JAK2 an FDA-approved treatment option for the management of moderate-to-severe alopecia areata, autoimmune non-scarring alopecia." (PMID 40383754, 2025).
endothelial dysfunction (10 papers, 2021 to 2026). In vascular diseases, endothelial dysfunction is a systemic pathological state of the endothelium (the inner lining of blood vessels) and can be broadly defined as an imbalance between vasodilating and vasoconstricting substances produced by (or acting on) the endothelium. "The JAK2 mutation contributes to elevated cardiovascular risk through enhanced chronic inflammation, oxidative stress, and endothelial dysfunction." (PMID 40243730, 2025). "Patients with MPNs, especially those with JAK2 mutations, are at increased risk of thrombotic events due to several mechanisms, including hyperviscosity, increased platelet activation, and endothelial dysfunction." (PMID 39877786, 2024). "In conclusion, Cbl alleviates endothelial dysfunction by inactivation of the JAK2/STAT4 pathway and inhibition of Runx3 expression in DM." (PMID 34798872, 2021). "Herein, we aimed to determine whether E3 ubiquitin ligase casitas B-lineage lymphoma (Cbl) alleviates endothelial dysfunction in DM rats by JAK2/STAT4 pathway." (PMID 34798872, 2021). "In conclusion, this study elucidates the mechanism that Cbl alleviates endothelial dysfunction in DM through inhibiting the JAK2/STAT4 pathway and Runx3 expression, providing novel insight into targeted therapy against DM and comprehensive understanding on DM progression." (PMID 34798872, 2021). "Astragaloside IV activates the JAK2/STAT3 and ERK1/2 signaling pathways, upregulates the expression of endothelial eNOS and the production of NO, and improves endothelial dysfunction." (PMID 34840664, 2021). "We additionally identified three genes (JAK2, GBP1, and TNFSF10) whose mRNA transcription suppression by Lp299v in PBMCs was inversely correlated with brachial FMD% suggesting a potential more direct role for these proteins in inflammation-induced endothelial dysfunction in humans." (PMID 33597583, 2021). "In a word, downregulation of JAK2 and STAT4 might alleviate endothelial dysfunction in DM rats." (PMID 34798872, 2021).